INS (insulin)
Diseases named in the same sentence as INS in open-access papers (continued):
Sharing a sentence is not in itself a finding about the gene and the disease.
Insulin resistance (continued). "This obesity is usually associated with hyperinsulinemia, followed by increased ovarian androgen secretion, which in turn causes visceral fat deposition, aggravating insulin resistance and further increasing androgen secretion due to elevated insulin levels." (PMID 37002532, 2023). "In epidemiological studies, vitamin D deficiency showed a strong relationship with insulin production and insulin resistance among T2DM patients." (PMID 37242192, 2023). "Insulin infusion is capable of suppressing TLR4, suggesting that, in addition, these molecules are associated with insulin resistance; high concentrations of insulin are also present in the pancreatic islets of obese animal models." (PMID 37373556, 2023). "Hypothalamic insulin resistance caused by overnutrition occurs more rapidly than in other insulin-sensitive tissues." (PMID 37886966, 2023). "Increasing age is associated with greater insulin resistance, while higher baseline fasting glucose indicates early signs of failure of beta-cell compensatory response in insulin production." (PMID 37794119, 2023). "Acquired insulin resistance is associated with decreased mitochondrial activity in response to insulin stimulation, while inherited insulin resistance is typically linked to reduced basal mitochondrial activity, possibly due to decreased mitochondrial content." (PMID 38313834, 2023). "Alterations in Wnt signaling have also been reported to cause insulin resistance in cultured preadipocytes, indicating a crosstalk between Wnt and insulin signaling." (PMID 37242132, 2023). "T2DM is involved in increased insulin resistance and insufficient insulin secretion, which are linked to gut microbiota [ref]." (PMID 37298483, 2023). "Some studies suggested that insulin resistance in endothelial cells was the main cause of coronary atherosclerosis, and BCAAs have been shown to upregulate glucose transporters and activate insulin secretion." (PMID 36984843, 2023). "The cause of T2D is insulin resistance or defective insulin action in peripheral tissues, hepatocytes, muscles, and fat tissues." (PMID 37623520, 2023). "Our research demonstrates that the expression patterns of several proteins associated with insulin signaling pathway are consistent with the change of insulin resistance after overexpression of G0S2." (PMID 37033250, 2023). "IL-6 was found to enhance insulin secretion in pancreatic islets and the associated hyperinsulinemia, suggesting that IL-6 plays a role in the pathogenesis insulin resistance." (PMID 37996879, 2023). "Ip3r1 deficiency in the skeletal muscle caused a worsening of HFD-induced insulin resistance, along with a significant elevation in blood glucose levels and plasma insulin levels in the fasting state." (PMID 36894534, 2023). "Age-related declines in insulin sensitivity and inadequate beta cell function compensate for rising insulin resistance are the primary contributing causes for this." (PMID 37813629, 2023). "Collectively these data powerfully indicate that CRP deficiency can improve insulin resistance and enhanced the influence of leptin on hepatic glucose kinetics and insulin signaling in PCOS rats." (PMID 37660067, 2023). "The impacts of VDRs (TaqI, BsmI, FokI, ApaI, and Cdx2 polymorphisms) on LH and SHBG concentrations, testosterone concentrations, insulin resistance, and plasma insulin concentrations have all been associated with the pathophysiology of PCOS." (PMID 37701195, 2023). "Past research has shown that polymorphisms in insulin-resistant genes are effective on insulin resistance and weight gain as well as on the risk of developing colon cancer." (PMID 37845622, 2023). "Many studies have reported its association with insulin secretion and insulin resistance, which leads to the development of type 2 DM." (PMID 36846642, 2023). "Serum Ca2+ dyshomeostasis is associated with the development of insulin resistance, reduced insulin sensitivity, and impaired glucose tolerance." (PMID 37999364, 2023).
Insulin resistance (continued). "Type 2 diabetes is a metabolic disease characterized by chronic hyperglycemia resulting from a progressive loss of β cell insulin secretion, frequently with the background of insulin resistance." (PMID 37371671, 2023). "Only two out of the seven FI-pPS associations, Preserved Insulin Secretion Cluster, and Insulin Resistance-Lipodystrophy Cluster were replicated among South Asian ancestry individuals, and none was observed in East Asian ancestry participants." (PMID 37790568, 2023). "Again, hypoinsulinenia can be caused by disorders like insulin hyposecretion and insulin resistance." (PMID 37525189, 2023). "The increase in short-term exposure to O3 was also observed to associate with the elevation of blood glucose and insulin level, and the occurrence of insulin resistance, which plays a vital role in the onset of type 2 diabetes." (PMID 37026147, 2023). "Bird and Hawley found that regular exercise reduces the risk of insulin resistance and also improves insulin sensitivity." (PMID 37894813, 2023). "Inflammatory cytokines cause insulin resistance, which is characterized by impaired insulin release and the disruption of insulin signal transduction, with the ultimate result of glucose imbalances." (PMID 37047820, 2023). "We also aimed to determine associations between baseline insulin levels and homeostatic model assessment for insulin resistance (HOMA-IR) and differential WL between the diets." (PMID 37813841, 2023). "Subjects with the risk allele (A) of the SNP were observed to have high insulin resistance and increased insulin secretion." (PMID 38033012, 2023). "To explore the impact of myeloid-CITED2 deficiency on HFD-induced insulin resistance, we performed glucose and insulin tolerance tests (GTT and ITT) by utilizing Lyz2cre and Cited2fl/fl:Lyz2cre mice." (PMID 37681868, 2023). "Insulin resistance, a hallmark of metabolic syndrome, is characterized by impaired insulin signaling and reduced glucose uptake by insulin-sensitive tissues, such as muscle and adipose tissue." (PMID 37445955, 2023). "Reduced insulin sensitivity (or greater insulin resistance) is a hallmark of normal physiology in late pregnancy and also underlies gestational diabetes mellitus (GDM) pathophysiology." (PMID 37961187, 2023). "TRAPseq on muscle microvascular endothelium will also be useful in other paradigms in mice in which muscle endothelial insulin transport is altered, such as in the setting of insulin resistance caused by diet-induced obesity." (PMID 37591837, 2023). "Preptin appears to regulate metabolic homeostasis via glucose-mediated insulin secretion enhancement and is, therefore, linked to insulin resistance." (PMID 37755271, 2023). "The intake of nuts and seeds did not seem to play a significant role in increasing blood glucose in this dietary pattern, although they have been associated with improvements in plasma insulin, insulin resistance and blood glucose." (PMID 37110190, 2023). "For a long time, insulin resistance and high insulin levels have been linked to increased levels of VLDL and triglycerides." (PMID 37552330, 2023). "In secretory cells, a downregulation of the insulin response pathway is also associated with higher BMI, in line with the insulin resistance observed in donors with obesity." (PMID 37291214, 2023). "The functions of IGF2BP2 are associated with insulin resistance, and insulin regulates the EGFR gene to promote the migration of human corneal epithelial cells." (PMID 37998047, 2023). "SLC7A11 expression is associated with higher insulin sensitivity in muscle and insulin resistance in adipose tissue." (PMID 38288471, 2023). "In skeletal muscle, intramyocellular diglyceride accumulation has been linked with insulin resistance, blunted insulin signalling and lipotoxicity." (PMID 36768137, 2023).
Insulin resistance (continued). "For instance, the lipid mediator palmitic acid has toxic effects in the islets, which activate the toll-like receptor to cause decreased insulin secretion and target organs’ insulin resistance." (PMID 37241737, 2023). "Insulin resistance causes an increase in circulating glucose leading to increased insulin secretion." (PMID 37772082, 2023). "Measures of inflammation (CRP), and glucose homeostasis (insulin, insulin resistance, and blood glucose) were associated with AgeAccel.Hannum, AgeAccelPheno, and AgeAccelGrim, but not with AgeAccel.Horvath." (PMID 36752898, 2023). "On the other hand, Type 2 DM is predominantly associated with insulin resistance, a condition where cells progressively lose their responsiveness to insulin." (PMID 38203517, 2023). "Patients with T2D and individuals at risk for the disease display impaired insulin-stimulated glycogen synthesis along with insulin resistance." (PMID 38027148, 2023). "In parallel with blood glucose assessment, plasma insulin determination also provides a chance to evaluate insulin peak and the presence of hyperinsulinism, which is largely associated with insulin resistance." (PMID 37754306, 2023). "A hallmark feature of CMS, insulin resistance refers to the reduced sensitivity of cells to insulin, the hormone pivotal for regulating glucose levels." (PMID 37868505, 2023). "Type 2 diabetes (T2DM) is characterized by insulin secretion deficiencies and systemic insulin resistance (IR) in adipose tissue, skeletal muscle, and the liver." (PMID 36333974, 2023). "CCL5 directly affects insulin signalling, and aggravates inflammatory responses in adipocytes, causing insulin resistance and obesity." (PMID 37778719, 2023). "For example, saturated fatty acids can induce insulin resistance by reducing the release of adiponectin and disrupting insulin signaling pathways associated with glucose uptake in adipose tissue." (PMID 37521997, 2023). "There is little information investigating which biological processes associated with T2D (e.g., insulin production, peripheral insulin resistance, inflammation) are most relevant for the genetic differences between the sexes and the time of T2D onset." (PMID 37291636, 2023). "Inflammation in obesity is strongly linked to insulin resistance; and inflammatory markers interfere with insulin signaling pathways through activation of JNK and MAPK or IKK/NF-κB pathways." (PMID 37081489, 2023). "In their study insulin secretion increased to compensate insulin resistance caused by atorvastatin during their trial." (PMID 37795366, 2023). "Serum concentrations of leptin and insulin were determined using the enzyme-linked immunosorbent assay method (ELISA), and insulin resistance was calculated using the homeostatic model assessment for insulin resistance (HOMA-IR)." (PMID 37110228, 2023). "In human, DNA methylation has been recently linked to liver and insulin metabolism as well as insulin resistance." (PMID 38010265, 2023). "The synergistic effects of obesity and sarcopenia on glucose metabolism and insulin sensitivity cause dyslipidemia, glucose intolerance, and insulin resistance." (PMID 37681878, 2023). "Insulin resistance (IR) is the progressive failure of skeletal muscle, adipose tissue, and the liver to respond to insulin, and is a major risk factor for type 2 diabetes." (PMID 36807886, 2023). "Apart from that, type B insulin resistance syndrome causes insulin resistance by autoantibodies blocking the binding sites of insulin on IR." (PMID 37664840, 2023). "Higher baseline cfPWV is associated with higher fasting insulin, insulin resistance, and beta cell function, and cfPWV increase is directly related with the 7-year progression in HDL-C and triglycerides in youth." (PMID 38075050, 2023). "Epigenetic changes are also implicated in the two basic pathogenic components of T2DM, namely insulin resistance and impaired insulin secretion." (PMID 37313245, 2023).
Insulin resistance (continued). "Here, we have established that DNER is expressed within pancreatic β-cells, and that loss of DNER leads to glucose intolerance, decreased insulin secretion and insulin resistance in adult mice." (PMID 37223028, 2023). "PCOS causes alterations in follicular endocrine signalling; insulin resistance (IR), impaired insulin, and ovarian hyperandrogenism can impair follicular activation, survival, growth, and selection." (PMID 36751233, 2023). "We also investigate the effect of Zfyve28 on insulin sensitivity in mice, showing that Zfyve28 knockout in mice can significantly improve insulin sensitivity and other indicators associated with insulin resistance." (PMID 37884540, 2023). "In contrast, T2D is attributed to a continuous loss of β-cell insulin secretion, often in the context of insulin resistance." (PMID 36896239, 2023). "While Zfyve28 overexpression impairs insulin sensitivity and causes lipid accumulation, Zfyve28 knockout in mice can significantly improve insulin sensitivity and other indicators associated with insulin resistance." (PMID 37884540, 2023). "Since diminished hippocampal insulin signaling leads to memory impairment, insulin resistance and hyperinsulinemia are probably associated with Alzheimer’s disease (AD)." (PMID 37275760, 2023). "Insulin resistance and insulin secretion are linked because insulin resistance is compensated for by increased insulin secretion, revealing a hyperbolic function." (PMID 37781697, 2023). "In recent years, Sirtuin 1 has been shown to be associated with insulin resistance and to be important for glucose-dependent insulin secretion and the protection of pancreatic β-cell mass." (PMID 37854188, 2023). "Plasma FFAs, BCAAs, and C3/C5 acylcarnitines have been implicated in causing insulin resistance, but their plasma concentrations are also regulated by insulin." (PMID 37159276, 2023). "Differential expression of miRNAs in HC and HS_MS2 groups associated with insulin signaling pathway and insulin resistance of common carp (n = 6)." (PMID 37091861, 2023). "Hepatic insulin resistance refers to a decrease in the sensitivity of the liver to insulin, causing gluconeogenesis and hyperglycaemia." (PMID 37830511, 2023). "It is unlikely that raised GLP-1 concentrations caused insulin resistance, however, as outside of pregnancy they are thought more likely to be involved in increasing insulin sensitivity than reducing it." (PMID 37439859, 2023). "Elevated oxidative stress levels in cellular senescence enhance insulin resistance and other effects, which caused the inability of insulin to achieve normal metabolic effects, ultimately leading to further MetS deterioration." (PMID 37868908, 2023). "Notable, insulin concentration and insulin resistance are affected by causal factors, including diet, lifestyle, and obesity." (PMID 38026570, 2023). "Thesecond one called as PPAR-γ2 which is specific to adipose tissues is linked to insulin resistance.Pro12Ala polymorphism is widely believed to be linked toincreased insulin sensitivity." (PMID 37928491, 2023). "Excess visceral adiposity and increased systemic inflammation are associated with insulin resistance, which is the reduced capacity for insulin-stimulated glucose uptake in metabolically active tissues such as adipose tissue and skeletal muscle." (PMID 37396595, 2023). "IL-6 is a pleiotropic cytokine with respect to insulin resistance; while numerous studies have indicated its association with insulin resistance, others have reported its insulin-sensitizing effects." (PMID 37876013, 2023). "In particular, plasma glutamate levels showed a positive correlation with glucose and insulin metabolism, and were associated with insulin resistance and increased risk of type 2 diabetes." (PMID 37314019, 2023). "Insulin-mediated glucose uptake in the skeletal muscle is profoundly susceptible to insulin resistance, which significantly contributes to obesity-related insulin resistance and type 2 diabetes." (PMID 37047820, 2023).
Insulin resistance (continued). "Obesity, characterized by excessive body fat accumulation, is a significant risk factor for T2D due to insulin resistance and impaired insulin secretion." (PMID 37600709, 2023). "Inflammation contributes to this process by affecting the way insulin signals are transmitted within the cells, making it harder for the body to respond to insulin effectively, an outcome called insulin resistance, a hallmark of T2DM." (PMID 37371102, 2023). "Mg2+ plays a key role in maintaining β cell health, and while Mg2+ deficiency impairs insulin secretion and promotes insulin resistance, its supplementation improves β cell function." (PMID 36574297, 2023). "Loss of critical mass and histology of insulin-secreting cells, fasting hyperglycemia, and insulin resistance are secondary events to immune system activation and autoantibody generation." (PMID 36670995, 2023). "Insulin resistance and dysregulation of glucose metabolism as a consequence of impaired insulin action and secretion, along with metabolic susceptibility and genetic predisposition, have the main role in the pathogenesis of T2D." (PMID 37316867, 2023). "In both type 1 and 2 diabetes patients, reduced or deficient insulin secretion and insulin resistance contribute to hypertriglyceridemia, as the enzymatic activity of lipoprotein lipase (LPL) depends on insulin action." (PMID 37448184, 2023). "NAFLD is often associated with insulin resistance, and fasting blood glucose and fasting insulin levels in mice were measured." (PMID 36986084, 2023). "Behind this, insulin resistance is increased in obese people due to abdominal fatness, causing an increase in insulin production in the pancreas (hyperinsulinemia occurs)." (PMID 38137870, 2023). "Despite the consistent observation that heavy drinking causes systemic insulin resistance in rodents, the discrepancy remains regarding the alterations of proteins involved in insulin signaling pathways." (PMID 36979389, 2023). "On the other hand, type 2 DM (T2DM), which accounts for about 90% of all cases of DM, is characterized by a partial or complete loss of insulin sensitivity in body cells and tissues, a mechanism called peripheral insulin resistance." (PMID 37298274, 2023). "A series of abnormalities related to insulin resistance such as B-cell dysfunction, increased blood glucose, impaired insulin secretion, and B-cell apoptosis can be caused by excessive triglyceride and low HDL-c levels." (PMID 37434259, 2023). "The VDR is significantly expressed in pancreatic β-cells, and studies have linked SNPs in the VDR gene to insulin resistance and insulin secretory capacity." (PMID 37836571, 2023). "Nevertheless, the concentration of TMAO showed a positive association with the fasting insulin concentration, a marker of insulin resistance." (PMID 36830968, 2023). "Subjects who had the reference allele in PPARGC1A and the variant allele of PPARγ exhibited higher fasting insulin levels, insulin resistance, and insulin area under the curve compared to those with the other combinations." (PMID 37513946, 2023). "AD-related brain insulin resistance is closely linked to systemic insulin homeostasis disorders caused by pancreas and/or liver dysfunction." (PMID 36834741, 2023). "Due to numerous significant associations between glycans and insulin levels, we also aimed to investigate the potential relationship between insulin resistance and N-glycosylation." (PMID 37079606, 2023). "The greater sensitivity to insulin of ILK-deficient adipocytes suggests that the presence of this highly conserved intracellular protein is necessary for the development of insulin resistance." (PMID 37383542, 2023). "Uric acid has a role in the development of abnormal glucose metabolism by causing insulin resistance, impaired insulin secretion, and beta-cell dysfunction." (PMID 37764747, 2023). "It is worth mentioning that long-term fructose consumption causes insulin resistance and increased circulating levels of insulin." (PMID 36901725, 2023).